ATP6V1C1 (ATPase H+ transporting V1 subunit C1)
Description:
Subunit of the V1 complex of vacuolar(H+)-ATPase (V-ATPase), a multisubunit enzyme composed of a peripheral complex (V1) that hydrolyzes ATP and a membrane integral complex (V0) that translocates protons. V-ATPase is responsible for acidifying and maintaining the pH of intracellular compartments and in some cell types, is targeted to the plasma membrane, where it promotes acidification of the extracellular environment (By similarity). The V-ATPase complex also acts as an activator for mTORC1 on lysosomal membrane by promoting the guanine nucleotide exchange factor (GEF) of the Ragulator complex, thereby enabling mTORC1 recruitment. Subunit C is necessary for the assembly of the catalytic sector of the enzyme and is likely to have a specific function in its catalytic activity (By similarity).
Synonyms: ATP6C; ATP6D; VATC; Vma5
Tractability: Small molecule: a structure with a bound ligand is known. Antibody: UniProt places it where antibodies can reach, with high confidence; its Gene Ontology location is reachable by antibodies, with medium confidence. PROTAC: ubiquitination databases record sites on it; its protein half-life has been measured.
Gene: Protein-coding gene on chromosome 8 (103,021,063 to 103,073,051, forward strand). Ensembl gene ENSG00000155097.
Subcellular location: Cytoplasmic vesicle, secretory vesicle, synaptic vesicle membrane; Cytoplasmic vesicle, clathrin-coated vesicle membrane
Subcellular location (Human Protein Atlas): Nucleoplasm; Cytosol
Pathways (Reactome):
Transport of small molecules: Ion channel transport; Transferrin endocytosis and recycling
Cellular responses to stimuli: Amino acids regulate mTORC1
Developmental Biology: Regulation of MITF-M-dependent genes involved in lysosome biogenesis and autophagy
Immune System: ROS and RNS production in phagocytes
Signal Transduction: Insulin receptor recycling
Gene Ontology:
Molecular function: protein binding; proton-transporting ATPase activity, rotational mechanism; proton transmembrane transporter activity
Biological process: proton transmembrane transport; regulation of macroautophagy; synaptic vesicle lumen acidification
Cellular component: extracellular exosome; lysosomal membrane; cytosol; plasma membrane; proton-transporting two-sector ATPase complex; vacuolar proton-transporting V-type ATPase, V1 domain; apical part of cell; clathrin-coated vesicle membrane; extrinsic component of synaptic vesicle membrane; membrane; proton-transporting V-type ATPase complex; proton-transporting V-type ATPase, V1 domain; synaptic vesicle membrane
Genetic constraint (gnomAD): Loss-of-function variants: 34 observed, 38.95 expected, observed/expected ratio (o/e) 0.87, 90% interval 0.66 to 1.16. The upper end of that interval is the gene's LOEUF score, 1.16, which puts it in group 5 of 6, group 1 being the genes least tolerant of losing a copy. Missense variants: 254 observed, 386.09 expected, observed/expected ratio (o/e) 0.66, 90% interval 0.59 to 0.73. Synonymous variants: 129 observed, 139.95 expected, observed/expected ratio (o/e) 0.92, 90% interval 0.8 to 1.07.
Homologues: Orthologues: chimpanzee ATP6V1C1 (100% identical), macaque ATP6V1C1 (100% identical), pig ATP6V1C1 (98% identical), mouse Atp6v1c1 (98% identical), rat Atp6v1c1 (98% identical), guinea pig ATP6V1C1 (97% identical), tropical clawed frog atp6v1c1 (95% identical), rabbit ATP6V1C1 (93% identical), zebrafish atp6v1c1a (88% identical), zebrafish atp6v1c1b (82% identical), Drosophila melanogaster Vha44 (64% identical), Caenorhabditis elegans vha-11 (55% identical). Paralogues in human: ATP6V1C2 (62% identical).
Diseases named in the same sentence as ATP6V1C1 in open-access papers:
ATP6V1C1 is named in the same sentence as 33 diseases in open-access papers, as found by Europe PMC text mining. Sharing a sentence is not in itself a finding about the gene and the disease. The quoted sentences say what the papers report.
breast carcinoma (15 papers, 2014 to 2025). "Also, the Atp6v1c1, an isoform of the C subunit, is highly overexpressed or amplified in 34% of human breast cancer cases and is associated with poor survival, breast cancer growth, and BM formation." (PMID 30825056, 2019). "Bioinformatics analysis reveals that ATP6V1C1 expression is upregulated in a variety of tumors and serves as a hub gene in breast cancer." (PMID 40384877, 2025). "Based on this, we subjected the ATP6V1C1 inhibitor to breast cancer cells and we confirmed that inhibition of autophagy/lysosome by VAM sensitized cancer cells to chemotherapy through blockage of protective autophagy." (PMID 40384877, 2025). "AtP6V1C1 has been shown to promote breast cancer cell growth by upregulating V-ATPase activity and activating the mTORC1 pathway." (PMID 37031243, 2023). "Breast cancer growth and bone metastasis are prevented by silencing of ATP6V1C1, suggesting a potential therapy target." (PMID 33903282, 2021). "Over-expression of ATP6V1C1 has been observed in oral squamous cell carcinoma and breast cancer, and it plays a major role in carcinogenesis." (PMID 33380233, 2021). "ATP6V1C1 promotes the growth of breast cancer by activating the mTORC1 pathway and promotes bone metastasis by activating V-ATPase." (PMID 33194650, 2020). "The overexpression of ATP6V1C1 is seen in a variety of cancers, including breast cancer, oral cancer, and oral squamous cell carcinoma." (PMID 32992741, 2020). "The overexpression of atp6v1c1 facilitates filament actin arrangement in the metastasis of cancerous cells and proves an innovative target in the treatment of breast cancer metastasis." (PMID 32992741, 2020). "ATP6V1C1 is overexpressed cancer such as metastatic oral squamous cell carcinoma, oral cancer patients and breast cancer, and has a role in tumor progression and metastasis." (PMID 32545553, 2020). "Analysis of TCGA data shows that V-ATPase subunit Atp6v1c1 is overexpressed or amplified in 34% of human breast cancer cases, with a 2-fold decrease in survival at 12 years." (PMID 28504970, 2017). "The BrdU incorporation assay showed that both shRNA-1 and shRNA-2 mediated ATP6V1C1 knockdown significantly inhibited proliferation of the human breast cancer cell lines MDA-MB-231, MCF-7, and MDA-MB-435s compared to the scramble shRNA." (PMID 28504970, 2017). "Experiments show that lentiviral-shRNA mediated ATP6v1c1 knockdown in 4T1 mouse mammary cancer cells significantly reduces orthotopic and intraosseous tumor growth." (PMID 28504970, 2017). "Silencing of Atp6v1c1 prevents breast cancer growth and bone metastasis, indicating the potential multiple functions of Atp6v1c1 in normal cell functions and diseases." (PMID 26274612, 2015). "In this study, we found that the normal arrangement of filamentous actin is disrupted in Atp6v1c1-depleted 4T1 mouse breast cancer cells and in the ATP6V1C1-depleted human breast cancer cell lines MDA-MB-231 and MDA-MB-435s." (PMID 24454753, 2014). "We have reported our results in the ASMBR 2010 Annual Meeting as a poster, poster number was SA0127 and the title was “Inhibition of Atp6v1c1 (a Subunit of the V-ATPase) Expression Decreases 4T1 Mouse Breast Cancer Growth, Invasion and Osteolytic Lesion”." (PMID 24454753, 2014). "The results of our study suggest that high expression of Atp6v1c1 affects the actin structure of cancer cells such that it facilitates breast cancer metastasis." (PMID 24454753, 2014). "Also, in a mouse breast cancer model was shown that the Atp6v1c1 knockdown reduced invasion and migration." (PMID 33425736, 2020). "ATP6V1C1 may promote breast cancer growth and bone metastasis by regulating lysosomal V-ATPase activity in vivo and in vitro." (PMID 33194650, 2020).
breast carcinoma (continued). "A previous study showed that in addition to being an essential component of V-ATPases, Atp6v1c1 may regulate filament actin arrangement in breast cancer cells." (PMID 26274612, 2015). "The findings also indicate that Atp6v1c1 could be a novel target for breast cancer metastasis therapy." (PMID 24454753, 2014). "To further elucidate how ATP6V1C1 affects breast cancer progression, we constructed the ATP6V1C1 knockout (KO) cells and discovered that the number of acidic lysosomes in ATP6V1C1 knockout cells was significantly reduced, indicating that ATP6V1C1 was related to lysosome function." (PMID 40384877, 2025). "Thus, we sought to determine whether Atp6v1c1, as a component of the V-ATPase complex, is also required for mTORC1 activation stimulated by amino acids in breast cancer cells." (PMID 28504970, 2017). "Similarly, recent studies have demonstrated that ATP6V1C1 knockdown does not affect the growth of mouse embryonic fibroblasts, C3H10T1/2, while reducing the proliferation of breast cancer cells such as MCF-7, MDA-MB-231, and MDA-MB-435S." (PMID 31554233, 2019).
oral squamous cell carcinoma (7 papers, 2013 to 2022). "Atp6v1c1 expression in metastatic oral squamous cell carcinoma indicates that it has a significant role in cancer cell proliferation and metastasis." (PMID 29459674, 2018). "Over-expression of ATP6V1C1 had been found in oral squamous cell carcinoma." (PMID 33194650, 2020). "Studies have shown that ATP6V1C1 could be used as a marker of diagnosis and prognosis in oral squamous cell carcinoma." (PMID 33194650, 2020). "It has recently been shown that Atp6v1c1 (C1), an isoform of the v1c subunit, was the most strongly overexpressed V-ATPase subunit in metastatic oral squamous cell carcinoma suggesting that V-ATPase activity, and specifically ATP6v1c1, indeed facilitates tumor progression and metastasis." (PMID 28504970, 2017). "The ATP6V1C1 level is considerably high in oral squamous cell carcinoma." (PMID 23874428, 2013). "ATP6V1C1, an essential subunit of V-ATPase and a regulator of V-ATPase activity, was recently reported to be the most strongly overexpressed gene in oral squamous cell carcinoma compared to other subunits of V-ATPase, and it was suggested to control tumor growth and metastasis." (PMID 24454753, 2014).
esophageal squamous cell carcinoma (3 papers, 2022 to 2025). Esophageal squamous cell carcinoma (ESCC) is a type of esophageal carcinoma (EC) that can affect any part of the esophagus, but is usually located in the upper or middle third. "In esophageal squamous cell carcinoma, an increased ATP6V1C1 to ATP6V1C2 ratio, reflecting the upregulation of ATP6V1C1 and downregulation of ATP6V1C2, has been identified as a distinctive molecular characteristic of the disease." (PMID 40463372, 2025). "In esophageal squamous cell carcinoma (ESCC), it has been shown that the ATPase subunit of ATP6V1C1 inhibits autophagy and enhances radiotherapy resistance; in contrast, our report demonstrated that Nrf2 promotes ESCC resistance to radiotherapy through CaMKIIalpha-associated activation of autophagy." (PMID 36890567, 2023).
periodontitis (3 papers, 2015 to 2023). An acute or chronic inflammatory process that affects the tissues that surround and support the teeth. "Case in point, the AAV-mediated Atp6v1c1 knockdown genetherapy has been shown to effectively treat bone erosion andinflammatory bone damage caused by periodontitis in a mousemodel." (PMID 29162967, 2017). "In this study, we utilized novel adeno-associated virus (AAV)-mediated Atp6v1c1 knockdown gene therapy to treat bone erosion and inflammatory caused by periodontitis in mouse model." (PMID 26274612, 2015). "After hsa-miR-144-5p upregulation, MMD (monocyte to macrophage differentiation related) was downregulated most (log2FC = −2.16, Padj = 3.7 × 10−23), which is a known target of hsa-miR-144-5p, The periodontitis risk gene ATP6V1C1 was the fourth most downregulated gene." (PMID 37822091, 2023). "We hypothesized that Atp6v1c1 may be an ideal target to prevent the bone erosion and inflammation caused by periodontitis." (PMID 26274612, 2015). "The inflammation reduction in the AAV-sh-Atp6v1c1 treatment group may be due to the down regulation of IL-6 (a pro-inflammatory cytokine associated with periodontitis)." (PMID 26274612, 2015). "In this study, our data indicate that AAV-shRNA-Atp6v1c1 treatment can significantly attenuate the bone erosion and inflammation caused by periodontitis and suggest that Atp6v1c1 RNAi knockdown gene therapy could be a novel therapeutic approach for the treatment of periodontitis." (PMID 26274612, 2015). "Expression of known periodontitis risk genes CPEB1, ABCA1, and ATP6V1C1 was significantly repressed by hsa-miR-130a-3p, -144-3p, and -144-5p, respectively." (PMID 37822091, 2023). "Our present findings possess a critical insight into Atp6v1c1 osteoimmune function between bone resorption and inflammatory host responses mediated by bacterial pathogens in periodontitis." (PMID 26274612, 2015). "In our current study, we applied injections of AAV-sh-Atp6v1c1 to treat periodontitis-mediated bone resorption and inflammation." (PMID 26274612, 2015). "As a subunit of Atp6i that is expressed in both osteoclasts and immune cells such as macrophages and dendritic cells, Atp6v1c1 should have an osteoimmune function during the development of periodontitis." (PMID 26274612, 2015). "All of these results indicated that Atp6v1c1 knockdown reduces the expression level of genes related to osteoclast and inflammation, and reduces bone erosion and inflammation in periodontitis lesion areas." (PMID 26274612, 2015). "The efficiency of Atp6v1c1 inhibition may reflect the important function of the molecules in the development of periodontitis, in osteoclastic resorption and inflammatory processes that result in tissue damages, as well as in the formation of osteoclasts." (PMID 26274612, 2015). "In our current study, the results showed that AAV-sh-Atp6v1c1 not only prevents inflammation and bone erosion in periodontitis, but it may also be useful for other inflammatory diseases." (PMID 26274612, 2015). "AAV-mediated Atp6v1c1 knockdown dramatically reduced osteoclast numbers and inhibited the infiltration of dendritic cells and macrophages in the bacteria-induced inflammatory lesions in periodontitis." (PMID 26274612, 2015). "Because it has been reported that IL-1α knockdown may inhibit the circuits between inflammatory processes and bone resorption, AAV-sh-Atp6v1c1 treatment can interfere with this positive feedback also and reverse bone resorption in the progression of periodontitis." (PMID 26274612, 2015). "This study demonstrated that Atp6v1c1 RNAi knockdown gene therapy mediated by AAV-shRNA-Atp6v1c1 is a promising novel therapeutic approach for the treatment of bone erosion and inflammatory related diseases, such as periodontitis and rheumatoid arthritis." (PMID 26274612, 2015).
breast tumors (2 papers, 2017 to 2018). "We began by checking the human genomics data to find that ATP6v1c1 is a highly amplified and overexpressed V-ATPase subunit in breast tumors relative to other V-ATPase subunits, such as Atp6v1c2 and Atp6v0a3." (PMID 28504970, 2017). "Our study showed that Atp6v1c1 may regulate the activity of lysosomal V-ATPase and trigger bone metastasis and breast tumour growth and may be is a promising target in the treatment and control of breast cancer." (PMID 29459674, 2018).
gastric cancer (2 papers, 2016 to 2022). A primary or metastatic malignant neoplasm involving the stomach. "Limited studies indicate that INTS8 contains mutations in peripheral T cell lymphoma compared with non-malignant samples from 12 patients, and a combination of INTS8 with SULF1, ATP6V1C1, and GPR172A can be used to discriminate gastric carcinomas from adjacent noncancerous tissues." (PMID 27567667, 2016).
Parkinson’s (2 papers, 2023 to 2024). "The Atp6v1c1 gene has been shown to be downregulated in multiple neurodegenerative diseases including Alzheimer’s, Parkinson’s, and dementia." (PMID 38891920, 2024). "It was reported before that hsa-miR-144-3p and hsa-miR-144-5p regulate ABCA1 and ATP6V1C1 (Capstone Project: Data Science DSC180B; Genetic Overlap between Alzheimer’s, Parkinson’s, and healthy patients; replication project for the paper)." (PMID 37822091, 2023).
breast invasive carcinoma (1 paper, 2025). "The findings indicate a significant upregulation of ATP6V1C1 in most tumors (n=25), notably in breast invasive carcinoma (BRCA), pancreatic adenocarcinoma (PAAD), and liver hepatocellular carcinoma (LIHC)." (PMID 40384877, 2025).
craniosynostosis (1 paper, 2023). Craniosynostosis is defined as the premature fusion of one or more cranial sutures leading to secondary distortion of skull shape resulting in skull deformities with a variable presentation. "Among the four novel loci (ZIC1, PRKAR1A, AZIN1/ATP6V1C1, GLRX3), there are factors implicated in intramembranous ossification and as we show, inherent to craniosynostosis processes." (PMID 37402774, 2023). "Functional follow-up with zebrafish models provided robust evidence for the implication of PRKAR1A, ZIC1 and ATP6V1C1 in the mineralization of the skull and pointed to a conceivable role of these genes in craniosynostosis." (PMID 37402774, 2023).
hepatocellular carcinoma (1 paper, 2015). A malignant tumor that arises from hepatocytes. "Interestingly, overexpression of the ATP6V1C1 subunit has been detected in several tumors such as oral squamous, pancreatic and hepatocellular carcinomas." (PMID 26356814, 2015).
liver fibrosis (1 paper, 2019). "ATPase H+ transporting V1 subunit C1 (Atp6v1c1) was increased in liver fibrosis, while down-regulated after the recovery in mice, and negatively regulated by MIR29a in LX-2 cells." (PMID 30781750, 2019). "Collectively, MIR29a plays an important role during the trans-differentiation of aHSCs in the resolution of liver fibrosis, in part, through regulation of ATP6V1C1." (PMID 30781750, 2019). "The expression of Atp6v1c1 was negatively correlated with Mir29a in CCl4-induced liver fibrosis in mice as well as in human HSC in vitro." (PMID 30781750, 2019). "MIR29a plays an important role during the resolution of liver fibrosis, which may be through the regulation of ATP6V1C1." (PMID 30781750, 2019). "We hypothesized that MIR29a promotes the resolution of liver fibrosis, and ATP6V1C1 may be a potential target of MIR29a." (PMID 30781750, 2019). "Thus, ATP6V1C1 may be regulated by MIR29a and promote the fibrogenesis while inhibiting the lipogenesis progress during liver fibrosis." (PMID 30781750, 2019).
lung adenocarcinoma (1 paper, 2013). A carcinoma that arises from the lung and is characterized by the presence of malignant glandular epithelial cells. "We have discovered ATP6V1C1, MYBBP1A, MACF1 and MYO10 upregulation in lung adenocarcinoma and accordingly, it is concluded that these genes have an important role in lung adenocarcinoma metastasis and we have reported all the mentioned genes for the first time in lung adenocarcinoma." (PMID 23874428, 2013).
methamphetamine dependence (1 paper, 2025). A drug dependence that is a psychological dependency on the regular use of methamphetamine. "In contrast, ROC curve analysis indicated no diagnostic significance for methylation in the ATP6V1C1, CIZ1, GNG7 and LIAS genes concerning methamphetamine dependence." (PMID 41368944, 2025).
osteopetrosis (1 paper, 2019). Osteopetrosis, also known as marble bone disease, is a descriptive term that refers to a group of rare, heritable disorders of the skeleton characterized by increased bone density on radiographs. "Genetic studies implicate a critical role for subunits ATP6V1B2, ATP6V1C1, ATPV0D2, and ATP6V0A3 (TCIRG1) in osteoclast activity as relevant mutations lead to osteopetrosis." (PMID 30804932, 2019).